PRMT5 (protein arginine methyltransferase 5)
Diseases named in the same sentence as PRMT5 in open-access papers (continued):
Sharing a sentence is not in itself a finding about the gene and the disease.
prostate carcinoma (continued). "Remarkably, in a bioluminescent imaging (BLI)-based lung metastasis mouse model, established by tail vein injection of prostate cancer cells with stable ZMYND11 knockdown, treatment with PRMT5 inhibitors EPZ015666 or GSK3326595 substantially reduced lung metastasis." (PMID 39341825, 2024). "The oncogenic effect of PRMT5-mediated FUBP1 methylation is unlikely to be limited to prostate cancer." (PMID 39146021, 2024). "It has been reported that DDR genes in prostate cancer cells get upregulated by PRMT5 upon radiation treatment independent of AR." (PMID 36959798, 2023). "We also reported that prostate cancer cells require PRMT5 to repair IR-induced DNA damage independent of AR." (PMID 36959798, 2023). "Our lab has previously reported that PRMT5 cooperates with its cofactor PICln in the epigenetic upregulation of genes that take part in DDR and contribute to the radioresistance acquisition in prostate cancer cells." (PMID 36959798, 2023). "PRMT5 gets upregulated and promotes DDR upon radiation treatment in prostate cancer cells." (PMID 36959798, 2023). "The critical roles of PRMT4, PRMT5, PRMT7, and hnRNPA1 in cell growth were also demonstrated in HCT 116 cells, a colon cancer cell line, and LNCaP, a prostate cancer cell line." (PMID 33782401, 2021). "The authors also showed that inducible knockdown of PRMT5 inhibits growth of AR-positive but not AR-negative prostate cancer cells as well as xenograft tumors in an AR-dependent manner." (PMID 30613353, 2018). "Similarly, pharmacological inhibition of PRMT5 decreased symmetric methylation of H4R3, expression of AR in AR-positive prostate cancer cells, and reduced cancer cell growth." (PMID 30613353, 2018). "The functional role of PRMT5 in the cytoplasm and nucleus and the relationship of its subcellular localization to prostate cancer have not been investigated." (PMID 22952863, 2012). "PRMT5 physically interacts and forms a complex with p44/MEP40/WD45/WDR77 in various cells, including prostate cancer cells, and co-localized with p44 in the cytoplasm of prostate cancer cells." (PMID 22952863, 2012). "Thus PRMT5 localization (predominantly cytoplasmic) in prostate cancer does not correspond with its role in ID4 methylation or association with CpG islands, which as one would expect to be in the nucleus." (PMID 25115397, 2014). "However direct evidence demonstrating the ID4 gene expression is independent of PRMT5 in prostate cancer remains to be investigated." (PMID 25115397, 2014). "PRMT5 could also target nonhistone substrates in cancer; for example, it can methylate arginine residues on the androgen receptor (AR) in prostate cancer and regulate prostate cancer malignancy." (PMID 30922330, 2019).
glioma (45 papers, 2013 to 2026). A benign or malignant brain and spinal cord tumor that arises from glial cells (astrocytes, oligodendrocytes, ependymal cells). "Although the attained results suggest an association between glioma growth and PRMT5 activity, only one phase-Ι study of the PRMT5 inhibitor (PRT811) has been registered to date." (PMID 36146527, 2022). "Evidence supports strong nuclear staining of PRMT5 to be associated with aggressive behavior and poor prognosis in patients diagnosed with high grade glioma and neuroblastoma cancers." (PMID 33989303, 2021). "PRMT5 is overexpressed in gliomas and is associated with poor prognosis." (PMID 40450009, 2025). "PRMT5 activity is inhibited in MTAP-deficient glioma cells, which, in turn, downregulates the expression of E3 ubiquitin ligase SMURF2, leading to decreased stability of downstream histone H2AX and ultimately resulting in the genomic instability of tumor cells." (PMID 40450009, 2025). "High PRMT5 expression in gliomas is closely associated with tumor aggressiveness." (PMID 40450009, 2025). "Furthermore, in a glioma cell line, PRMT5 deficiency induced expression of inhibitors of differentiation (Id) namely, Id2 and Id4." (PMID 33440687, 2021). "Interestingly, increased expression of PRMT5 positively correlates with high-grade glioma malignancy and is inversely associated with patient survival." (PMID 31694585, 2019). "In glioma models, dual inhibition of PRMT5 and MAT2A produced a synergistic synthetic lethal effect, markedly suppressing tumour growth and prolonging survival." (PMID 41537447, 2026). "Patient-derived glioma stem-like cells (GSCs), treated with PRMT5 inhibitor (LLY-283) or transfected with PRMT5-target-specific siRNA, were treated with TMZ and subjected to in vitro functional and mechanistic studies." (PMID 41986321, 2026). "Tissue microarray analysis revealed that the extent of DAB staining for MTAP and PRMT5 was generally higher than that for MAT2A in glioma samples." (PMID 40450009, 2025). "For instance, lncRNA LINC00515 sequesters miR-16, releasing its inhibition on PRMT5 and promoting glioma progression." (PMID 41204384, 2025). "Numerous studies have confirmed that PRMT5 can promote the malignant progression of gliomas through multiple pathways, indicating it to be a potential therapeutic target." (PMID 40450009, 2025). "The PRMT5 inhibitor required more time to take effect in the 3D glioma organoid model, with the organoid structure collapsing from the outermost cells inward, suggesting the gradual penetration of the drug." (PMID 40450009, 2025). "PRMT5 and MAT2A show promise as a combined target in gliomas where 5′-methylthioadenosine phosphorylase (MTAP) deficiency accounts for approximately 30%." (PMID 40450009, 2025). "When using the combination therapy, inhibition of the proliferation of the glioma cell line or promotion of apoptosis with the PRMT5 inhibitor led to a delayed onset of action." (PMID 40450009, 2025). "Then, we simulated the inhibitory effect of PRMT5/MTA inhibitor on GBMs by in vitro and in vivo experiments in which MTAP‐deficient glioma cells coexisted with microglia and neurons with normal MTAP expression." (PMID 39711357, 2024). "PRMT5 is usually regarded as a marker of malignant progression in gliomas, and its expression increases simultaneously with malignant progression." (PMID 39711357, 2024). "PRMT5 gene expression varies in different grades of glioma: low in low-grade gliomas and high in malignant gliomas." (PMID 38827324, 2024). "PRT811 is a selective and orally bioavailable PRMT5 inhibitor that passes the blood–brain barrier and shows effectiveness in high-grade glioma." (PMID 38136401, 2023). "Specifically, increased PRMT5 expression and activity contribute to the silencing of several tumor suppressor genes in glioma cell lines." (PMID 37861293, 2023).
glioma (continued). "PRMT5 protein is overexpressed in several epithelial tumors, including breast and lung cancer, as well as in hematologic malignancies and glial tumors." (PMID 37861293, 2023). "TCGA datasets showed that PRMT5 levels are significantly higher in glioma than in normal brain tissues, and high PRMT5 levels predict poor prognosis in glioma patients." (PMID 37822160, 2023). "The expression of protein arginine methyltransferase 5 (PRMT5) is negatively correlated with the survival rate of glioma patients." (PMID 36146527, 2022). "The role of PRMT5 is not only critical to glial cell differentiation but also is important in human glioma progression." (PMID 33440687, 2021). "Results indicated that SNHG16 can perform as an oncogene by sponging miR-4518 leading to the upregulation of PRMT5 expression in glioma." (PMID 33440687, 2021). "Previously, our group showed that CMP5 is efficacious in inhibiting PRMT5 activity in an in vitro GBM model as well as an in vivo glioma zebrafish model." (PMID 33440687, 2021). "Investigators, including our group, have demonstrated that an increase in PRMT5 expression is associated with a worse GBM prognosis; furthermore, studies have reported a direct correlation between PRMT5 expression and grade of glioma malignancy." (PMID 33440687, 2021). "Expression of PRMT5 correlates with grade of malignancy in gliomas and inversely correlates with survival." (PMID 33579912, 2021). "We have demonstrated that PRMT5 expression is low in normal glial cells and low grade glioma but highly expressed in GBM, and its expression increases with increasing malignant." (PMID 33807786, 2021). "Downregulation of PRMT5 resulted in decreased glioma cell proliferation and inhibition of tumor formation." (PMID 34065983, 2021). "EPZ015666, the other inhibitor of PRMT5, can inhibit the PRMT5 mediated SDMA methylation of hnRNP A1 in gliomas." (PMID 32859239, 2020). "miR-1266 in PC and miR-16 and miR-4518 in glioma have been suggested to negatively regulate PRMT5 expression." (PMID 32743345, 2020). "Of those, miR-16 and miR-4518 regulation of PRMT5 in glioma can be outcompeted by the long noncoding RNA (lncRNAs) LINC00015 and SNHG16, respectively." (PMID 32743345, 2020). "In high-grade gliomas, PRMT5 is highly expressed, and its expression inversely correlates with patient survival." (PMID 31652645, 2019). "As previously reported, lncRNA SNHG16 acts as an oncogene by sponging miR-4518 and up-regulating PRMT5 expression in glioma cells." (PMID 30691465, 2019). "Increased PRMT5 expression and activity contribute to silencing of several tumour suppressor genes in glioma cell lines." (PMID 29946150, 2018). "PRMT5 levels positively correlate with malignancy and negatively correlate with glioma patients’ survival, therefore justifying the efforts to identify specific pharmacological inhibitors as potential therapeutic targets." (PMID 30026560, 2018). "High levels of Prmt5 were detected in proliferating OPCs, OliNeu, and glioma cells and lower transcripts in differentiating OPCs." (PMID 30026560, 2018). "It is worthy of note that knockdown of PRMT5-another methyltransferase targeting arginine residues on histone tails- had a similar effect on the clonogenic potential and viability of glioma cells." (PMID 25602259, 2015). "Therefore, PRMT5 is considered a potential therapeutic target to treat gliomas, and the development of PRMT5 inhibitors is gaining popularity in cancer research." (PMID 40450009, 2025). "For validation, the effect of the PRMT5 inhibitors LLY-283 and GSK591 on cell viability was confirmed using full growth inhibition curves in five patient-derived H3K27M DMG cell lines, as well as in a sixth paediatric glioma line with a H3G34R mutation." (PMID 38172189, 2024).
glioma (continued). "Still, PRMT5 inhibitors are increasingly studied in the context of both GB cell lines and primary cells, and some reports also indicate inverse correlation between the PRMT5 expression levels and survival of patients with glioma or GB diagnosis." (PMID 38383756, 2024). "Finally, we hope that this study will provide some experimental basis for the role of PRMT5/MTA inhibitors in the treatment of gliomas." (PMID 39711357, 2024). "Multiplexed immunofluorescence staining also reflected the expression of PRMT5 in glioma." (PMID 39711357, 2024). "PRMT5 inhibitor has also been shown to sensitize glioma cells to radiation and chemotherapies." (PMID 38827324, 2024). "There is evidence to suggest that the growth of glioma may be reliant on PRMT5 expression, making it a potential therapeutic target." (PMID 38827324, 2024). "Similarly, HOXC10 overexpression promotes angiogenesis in human gliomas through interaction with PRMT5 and upregulation of VEGFA expression in vitro." (PMID 36531217, 2022). "Interestingly, PRMT5 was required for the overexpression of VEGFA mediated by HOXC10 representing a potential target for anti-VEGF therapy in glioma therapeutics." (PMID 33440687, 2021). "Treatment of glioma cells with a PRMT5 inhibitor led to cell cycle arrest and senescence in vitro." (PMID 34065983, 2021). "Moreover, SNHG16 promotes glioma tumorigenesis by acting as the ceRNA that upregulates the expression of the miR-4518 targeted gene, protein arginine methyltransferase 5 (PRMT5) by directly sponging miR-4518." (PMID 33980320, 2021). "However, it has been suggested that a PRMT5 inhibitor may increase the sensitivity of glioma cells to chemotherapies." (PMID 38827324, 2024). "In addition, high levels of MYC and PRMT5 correlate with glioma malignancy." (PMID 31694585, 2019). "For example, in retinoblastoma, PRMT5 promotes VEGF transcription by enhancing H3K4me3 at its promoter, and in gliomas, it cooperates with HOXC10 and WDR5 to upregulate VEGF expression." (PMID 41204384, 2025). "In phenotypic experiments, PRMT5 inhibitors reduced SDMA levels, inhibited cell proliferation, and promoted apoptosis in glioma models." (PMID 40450009, 2025). "This approach sets the stage for the further investigation of the therapeutic potential of targeting PRMT5 and MAT2A in glioma." (PMID 40450009, 2025). "Further validation using immunofluorescence and western blotting confirmed that PRMT5 and MAT2A were consistently overexpressed in glioma cell lines, supporting their potential as inhibitor targets in future studies." (PMID 40450009, 2025). "Overexpressed HOXC10 can interact with PRMT5 to promote the expression of VEGF, thereby promoting angiogenesis in gliomas and increasing the metastasis and invasion abilities of gliomas." (PMID 35201457, 2021). "Protein arginine methyltransferase 5 (PRMT5) is another candidate gene for the diagnosis and treatment of glioma, its nuclear expression correlates with poor survival in glioma patients." (PMID 30498431, 2018). "Our study proved the combination of PRMT5 and MAT2A inhibitors may induce synthetic lethality by downregulating the PI3K-AKT pathway, indicating the potential of this approach in treating gliomas." (PMID 40450009, 2025). "On the one hand, inhibiting PRMT5 activity can promote cell cycle arrest and the apoptosis of tumor cells, reducing its metastatic capability; on the other hand, it can restore the expression of tumor suppressor genes such as ST7 and PTEN in gliomas." (PMID 40450009, 2025). "This study explored the combined effects of PRMT5 and MAT2A inhibitors on glioma progression." (PMID 40450009, 2025). "In recent studies, high levels of PRMT5 and MYC corelate with glioma malignancy." (PMID 38136401, 2023). "Increased expression of PRMT5 is common in high-grade gliomas, with a negative correlation with patient survival." (PMID 35406768, 2022).
glioma (continued). "In vitro and in vivo studies demonstrated that one of PRMT5 inhibitors leads to a non-replicative senescence and apoptosis of glioma cells." (PMID 31652645, 2019).
leukemia (45 papers, 2009 to 2025). A malignant (clonal) hematologic disorder, involving hematopoietic stem cells and characterized by the presence of primitive or atypical myeloid or lymphoid cells in the bone marrow and the blood. "Given the promising pre-clinical results of PRMT5-i in leukemia, our findings suggest that SETD2 mutation status should be considered in treatment strategies." (PMID 40300107, 2025). "Although PRMT5-i have shown promise in treating MLL-r leukemia, our results suggest that additional mutations, such as those in SETD2, should be considered for their potential impact on PRMT5-i efficacy." (PMID 40300107, 2025). "Protein arginine methyltransferase 5/1 inhibitors reduce spliceosome methylation and inhibit splicing, and leukemias with splicing factor mutations are preferentially sensitive to PRMT5 inhibition." (PMID 36009519, 2022). "In keeping with this, conditional deletion or small molecule inhibition of PRMT5 impaired leukemia development and implicated PRMT5 as an enforcer of the leukemic differentiation block." (PMID 31552175, 2019). "In MDS1 and EVI1 complex locus (EVI1)-overexpressing leukemia, PRMT5 inhibition decreased the levels of the spliced cytoplasmic form of activating transcription factor 4 (ATF4) protein, resulting in increased oxidative stress, growth arrest and senescence." (PMID 40603833, 2025). "In CML, PRMT5 inhibition decreases leukemia stem cell survival and self-renewal by promoting DVL3 degradation and weakening Wnt/β-catenin signaling." (PMID 41204384, 2025). "Several studies have highlighted the role of PRMT5 as a tumor-promoting factor in several types of cancers, including colon, breast, lung, leukemia, and pancreatic cancers among others." (PMID 39201539, 2024). "Deletion or pharmacological inhibition of Prmt5 improved survival of a mouse AML1-ETO leukemia model and inhibited the growth of AML patient-derived xenografts." (PMID 39478125, 2024). "In the context of MLL-fusion leukemia, the PAF (Polymerase Associated Factor) complex facilitates the transcriptional regulation of PRMT5, which is essential for the maintenance and progression of the leukemia." (PMID 39255317, 2024). "The overexpression of PRMT5 leads to an increase in leukemia cell growth, especially in FLT3-ITD primary blasts compared to FLT3-WT patients." (PMID 36358861, 2022). "Recently, it has been shown that targeting methyltransferase PRMT5 eliminates leukemia stem cells in chronic myelogenous leukemia." (PMID 32517078, 2020). "There is a lot of promise and excitement surrounding epigenetic therapies, and clinical PRMT5 inhibitors have entered phase one trials for leukaemia treatment." (PMID 29876520, 2018). "The relative phosphorylation of PRMT5 at Thr80 in cancer tissues were significantly elevated in all cases escpecially in the leukemia, lung, colon and breast cancer carcinoma as well as in HCC tissues." (PMID 28074910, 2017). "Collectively, these results link attenuated PRMT5 activity to the short-lived oncogenic stress response and leukemia development in FA HSPCs." (PMID 27507053, 2016). "Moreover, driver genes, as RAS, FLT3, NPM1, EVI1 and KMT2A shape the interaction between polyamine metabolic pathway and leukemia-supporting functions, resulting in selective vulnerabilities, as unveiled by drugs targeting PRMT5." (PMID 40603833, 2025). "Previously, PRMT5 has been shown to contribute to stem cell function in leukemia and glioblastoma." (PMID 39201539, 2024). "Moreover, significantly enriched genes in distinct Eμ-PRMT5 populations overlapped with PRMT5-expressing cells from human RT tumors, establishing a PRMT5-driven gene signature in aggressive mouse and leukemia." (PMID 36609611, 2023). "Importantly, preclinical PRMT5 inhibitors increase DNA damage and improve the sensitivity of leukemia cells to PARP or ATM inhibitors in vitro." (PMID 37861290, 2023).